MYCN (MYCN proto-oncogene, bHLH transcription factor)
Diseases named in the same sentence as MYCN in open-access papers (continued):
Sharing a sentence is not in itself a finding about the gene and the disease.
neuroblastoma (continued). "Different therapeutic approaches have been developed to treat neuroblastoma, but high-risk cases (that are often MYCN amplified) remain critical." (PMID 35490242, 2022). "Genomic amplification of the oncogene MYCN is a key oncogenic event in the development of high-risk neuroblastoma, which occurs in approximately half of all high-risk cases." (PMID 36077650, 2022). "International Neuroblastoma Risk Group uses histologic category, age, grade, MYCN status, DNA ploidy, etc., as a risk group for NBL patients, which helps to develop individualized treatment options according to different risk characteristics." (PMID 36419120, 2022). "Apparently, these results suggest that upregulated DEGs are enriched for oncogenic TFs in MYCN-associated tumors, such as neuroblastoma." (PMID 36139535, 2022). "High-risk neuroblastoma (NB) remains an extremely difficult subgroup to cure and is associated with MYCN amplification." (PMID 35018218, 2022). "High-risk neuroblastoma is designated based on the demonstration of clinically advanced stage or the presence of metastasis, age greater than 18 months at diagnosis, MYCN oncogene amplification, histology, and/or chromosomal ploidy." (PMID 36525420, 2022). "More recently, it was reported that loss of GAS7 expression accelerated metastasis of neuroblastoma harboring MYCN overexpression or amplification." (PMID 34201353, 2021). "Co-inhibition of Aurora-A and ATR (required for the stability of replication stalled forks) causes tumour regression and immune system activation in MYCN-amplified neuroblastoma animal models." (PMID 33981003, 2021). "Amplification of the oncogene MycN is frequent in neuroblastoma and is associated with a poor prognosis and rapid tumor progression 4,5." (PMID 33390782, 2021). "In 1997, transgenic overexpression of MYCN in neural crest cells was shown to cause neuroblastoma in mice, helping to clarify the role of MYCN in the genesis of this disease." (PMID 34769149, 2021). "This is typically the case for MYCN amplified (MNA) neuroblastoma, accounting for about 50% of the high-risk cases sharing a 50% 5-year survival rate.The driving role of MYCN in cancer was confirmed in genetically engineered mouse models." (PMID 34508175, 2021). "Overexpression of MYCN is associated with poor outcomes in patients with neuroblastoma and correlates with a high-risk phenotype." (PMID 33440687, 2021). "Various studies reported that c-Met/HGF signaling is affiliated with increased malignancy and stem cell enrichment in various cancers such as high-grade gliomas, high-risk medulloblastomas, and MYCN-amplified, high-risk neuroblastomas." (PMID 34055785, 2021). "While an increasing number of reports suggest an association of MYCN with epigenetic machinery, the mechanisms of these interactions are poorly understood in the neuroblastoma setting." (PMID 33968920, 2021). "At this point, two high-risk neuroblastoma groups are commonly considered: the MYCN amplified (20–25%) group and the more common 11q-deletion (35–45%) group, which together represent currently therapeutically challenging cases." (PMID 34885007, 2021). "MYCN activation is a hallmark of advanced neuroblastoma (NB) and a known master regulator of metabolic reprogramming, favoring NB adaptation to its microenvironment." (PMID 34183658, 2021). "The study population appropriately demonstrated the expected spectrum of pathological and cytogenetic risk features in neuroblastoma: 9/13 (70%) had stage 4 disease and 3/13 (23%) had MYCN amplification." (PMID 34722256, 2021). "MYCN amplification is of particular interest as it accounts for approximately 20% of neuroblastoma cases and is strongly associated with a malignant course of disease and poor survival, even in localized disease." (PMID 35008802, 2021).
neuroblastoma (continued). "In the past, several genetic factors have been found to correlate with unfavorable outcome in neuroblastoma, including loss of heterozygosity at chromosomes 1p, trisomy of 17q and the amplification of the N-myc proto-oncogene protein (MYCN)." (PMID 34771457, 2021). "The SK-N-DZ cell line represents high-risk neuroblastoma, with abundant expression of MYCN and IGF2BP1." (PMID 33796454, 2021). "Further, we show that by targeting ATR in combination with other drugs that cause replication stress, we can increase killing of both high-risk MYCN amplified and non amplified neuroblastoma." (PMID 34944835, 2021). "We have observed significant and durable responses to indisulam in multiple high-risk neuroblastoma models including PDXs derived from relapsed patient samples, transgenic MYCN/ALKF1178L mice, and tumors derived from C-MYC–overexpressing mice." (PMID 34788094, 2021). "International risk classification of neuroblastoma, based on clinical criteria plus MYCN amplification and recently complemented by transcriptomic parameters, has proven its usefulness for making therapy decisions and for disease management." (PMID 34202325, 2021). "Amplification of MYCN is used as a diagnostic parameter to classify neuroblastoma patients into stages and risk groups." (PMID 33659885, 2021). "Genomic amplification of the MYC oncogene family member MYCN characterizes a subset of high-risk pediatric neuroblastomas." (PMID 33525507, 2021). "Unfortunately, the cure rate for high-risk neuroblastoma, defined as MYCN-amplified (MYCN-A) tumors or a diagnosis over the age of 18 months with metastatic disease, remains lower than 50%." (PMID 35464627, 2021). "Here, we demonstrate that novel drugs targeting a protein called ATR can specifically kill a type of high-risk neuroblastoma associated with MYCN expression." (PMID 34944835, 2021). "Because MYCN has been shown to drive neuroblastoma pathogenesis, we used the high-risk gene signature (high-risk MYCN non-amplified subgroup) to predict potential target." (PMID 35056094, 2021). "Segmental chromosomal aberration is common in high-risk neuroblastoma, such as amplification of the MYCN oncogene deletions of chromosomes 1p, 3p, 4p, and 11q, and gains of chromosomes 1q, 2p, and 17q." (PMID 33465163, 2021). "MYCN gene amplification and upregulated expression are major hallmarks in the progression of high-risk neuroblastoma." (PMID 34026620, 2021). "Human ALKF1174L (analogous to mouse ALKF1178L) is the most frequent somatic mutation in neuroblastoma and is associated with MYCN amplification, conferring a worse prognosis than MYCN amplification alone." (PMID 34788094, 2021). "The presence of MYCN amplifications (MYC-Gain) automatically classifies neuroblastoma as high-risk and patients with this amplification are treated more intensely to increase the probability of overall survival." (PMID 34458583, 2021). "Though only found in 25% of neuroblastoma cases, MYCN amplification has been associated with poor prognosis and has remained one of the few genetic prognostic indicators of high-risk neuroblastoma." (PMID 33796454, 2021). "Neuroblastoma is the solid extra-cranial tumor associated with genetic defects in transcriptional factors MYCN, ALK, and PHOX2B, which play important role in sympatho-adrenal lineage development." (PMID 32748156, 2021). "Approximately 25% of human neuroblastoma is caused by amplification of the MYCN oncogene, which leads to overexpression of N‐Myc oncoprotein." (PMID 33497018, 2021). "Mono-, di- and tri-methylation at Histone 3 Lysine 27 by the HMT EZH2 is known to be specifically increased in neuroblastoma, particularly in MYCN amplified tumours, and also associated with poor patient outcome." (PMID 34064704, 2021). "MYC and MYCN have been implicated in other pediatric tumors, including neuroblastoma and medulloblastoma, often in subsets of high-risk tumors." (PMID 34552068, 2021).
neuroblastoma (continued). "In contrast, recent high-throughput genome-wide studies have revealed that there were few recurrent somatic alterations in high-risk neuroblastoma, except MYCN ALK ATRX and TERT." (PMID 33465163, 2021). "MYCN amplification as well as 1p and 11q deletions are significantly associated with poor prognosis for neuroblastoma patients, whereas hyperploidy is related to an excellent prognosis." (PMID 34796286, 2021). "In line with previous reports, MYCN amplification, a hallmark of high-risk neuroblastoma, showed little variation between spatially distinct samples, but pronounced differences in patient CB1003 between time points." (PMID 34815394, 2021). "Patients in the high GTscore group had an older age, MYCN amplification, advanced International Neuroblastoma Staging System stage, and high risk." (PMID 35071226, 2021). "High-risk neuroblastoma is associated with chromosomal alterations including 1p deletion, 11q deletion, 17q gain, MYCN amplification, and ALK-activating mutations." (PMID 34118691, 2021). "Telomere maintenance is essential for high-risk neuroblastomas and is comparable to MYCN-amplified tumors." (PMID 34069817, 2021). "In fact, MYCN amplification, occurring in around 25% of all primary neuroblastomas and in 30%–40% of all high-risk cases, has since long been known to correlate to poor clinical outcome." (PMID 33659885, 2021). "For all neuroblastomas, the presence of a MYCN amplification and chromosome 1p36 loss was determined by the reference laboratory of the German neuroblastoma study group using FISH analysis." (PMID 34442335, 2021). "Retinoic acid treatments of MYCN-amplified neuroblastoma cells have also been reported to cause differentiation and G1 arrest of these cells, although overexpression of MYCN counteracts G1 stop and retinoic-acid-induced differentiation." (PMID 34832966, 2021). "HLA-E is a stress-induced molecule, and its expression is significantly associated with high-risk neuroblastoma (Stage 4 and MYCN amplified cases)." (PMID 33968044, 2021). "In both the JoMa1 cell line and non-genetically modified neural crest cells, overexpression of MycN was proven sufficient to generate neuroblastoma upon transplantation in immune-deficient mice." (PMID 33718380, 2021). "MYCN amplification is commonly seen in high-risk neuroblastoma, rendering it highly malignant and recurrence prone." (PMID 34422720, 2021). "Generally, 11q-deletion and MYCN amplification do not co-exist in the same tumor, although rare cases that harbor both 11q deletion and MYCN amplification have been described and constitute a very high-risk group of neuroblastoma patients." (PMID 34885007, 2021). "Aberrant activation of MYCN, for instance, has been frequently linked to the development of neuroblastoma, retinoblastoma, leukemia, and, more recently, hepatocellular carcinoma." (PMID 34746136, 2021). "We have previously shown that THZ1, a covalent inhibitor of CDKs 7/12/13, leads to cytotoxicity in MYCN-amplified neuroblastoma through the downregulation of super-enhancer-associated transcriptional upregulation." (PMID 35198433, 2021). "Amplification of the MYCN oncogene among other molecular features, increase neuroblastoma aggressiveness and risk for relapse." (PMID 34192988, 2021). "Here, we show that MYCN amplified neuroblastoma cells are susceptible to C646 treatment, and that CBP targeting compounds should be further investigated as a single modality or combination therapeutic approach for high-risk neuroblastoma." (PMID 33968920, 2021). "In the present review, we focused on mutually exclusive genomic aberrations that are common to unfavorable neuroblastomas: MYCN amplification and 11q loss." (PMID 34069817, 2021).
neuroblastoma (continued). "Surprisingly, miR-34c expression was elevated in MNA tumors, although previous studies claimed that the MYCN-targeting miR-34 family is downregulated in high-risk neuroblastoma." (PMID 34026620, 2021). "Amplification of the MYCN transcription factor is a common feature of advanced neuroblastoma and associated with a poor outcome of the disease." (PMID 34423893, 2021). "In contrast to previous reports, suggesting downregulation of MYCN-regulatory miRNAs in MYCN-driven neuroblastoma, we observed a variety of known MYCN-targeting miRNAs among oncomiRs associated with MYCN amplification." (PMID 34026620, 2021). "A recent study identified a 37-gene signature of EZH228, which is repressed by EZH2 and silenced in MYCN-amplified high-risk neuroblastoma." (PMID 34893606, 2021). "Two independent reports recently reassessed the impact of 1p loss of heterozygosity on the development of MYCN-driven neuroblastoma." (PMID 34885007, 2021). "MYCN amplification plays a critical role in defining high-risk subgroup of patients with neuroblastoma." (PMID 34109133, 2021). "We have demonstrated that the ODC1 G316A polymorphism has functional significance in neuroblastoma and is subject to allele-specific regulation by the MYCN oncoprotein." (PMID 33918978, 2021). "MYCN-driven neuroblastoma accounts for about half of all high-risk cases, and next-generation sequencing has allowed for the identification of further mutually-exclusive subgroups of poor-outcome disease." (PMID 33808071, 2021). "High‐risk neuroblastoma (HR‐NB) is defined as any neuroblastoma (other than stage L1) harboring MYCN amplification or any patient older than 18 months of age at diagnosis with stage M disease." (PMID 33283381, 2021). "Telomerase activation is commonly observed in high-risk neuroblastoma, such as MYCN-amplified tumors and TERT-rearranged tumors." (PMID 34885007, 2021). "While MYCN amplification is conceptually easier to understand at the molecular level, the mechanisms underlying 11q-deletion in neuroblastoma have been elusive." (PMID 34885007, 2021). "One such tumor is neuroblastoma, which is characterized by a variety of driver events, including MYCN amplification and ALK mutations." (PMID 33718380, 2021). "Transcriptional profiling revealed that the major antagonistic programs driving gene expression in neuroblastoma are linked to either NTRK1 or MYCN expression." (PMID 34771457, 2021). "This is in keeping with previous analyses of neuroblastoma cases, which identified a correlation between coexistence of ALK activating mutations and MYCN amplification in high-risk neuroblastoma with poor prognosis." (PMID 34885007, 2021). "The MYCN oncogene is frequently amplified in high-risk neuroblastoma and a known biomarker for disease stratification." (PMID 34026620, 2021). "Telomere maintenance is a central hallmark of high-risk neuroblastoma, and approximately 50% of high-risk neuroblastoma harbour amplification of the MYCN oncogene." (PMID 34735429, 2021). "About 50% of high-risk neuroblastomas are MYCN amplified and a causational link between MYCN activation in the nervous system and tumourigenesis has been firmly established." (PMID 34847775, 2021). "The MYCN oncogene is amplified in 25% of neuroblastomas, and it has been linked to therapeutic resistance." (PMID 34577571, 2021). "Here, we discuss recently published reports regarding molecular mechanisms in the 11q-deletion and MYCN-amplified high-risk neuroblastoma groups." (PMID 34885007, 2021). "MYCN amplification is reliable marker for the high-risk neuroblastoma group and is prevalent in approximately 20% of patients with neuroblastoma." (PMID 34069817, 2021). "High ODC1 expression is found in MYCN-amplified neuroblastoma and is associated with a poor prognosis." (PMID 33918978, 2021).
neuroblastoma (continued). "Amplification of the MYCN oncogene plays a central role in the pathophysiology and clinical behavior of high-risk neuroblastoma and is associated with an increased vascular index and poor prognosis." (PMID 34832966, 2021). "Neuroblastoma is a devasting childhood cancer in which multiple copies (amplification) of the cancer-causing gene MYCN strongly predict poor outcome." (PMID 33918978, 2021). "This would open new possibilities to target using siRNAs certain genes related to neuroblastomas such as MYCN, which is overexpressed in more than 25% of high-risk diagnosed patients." (PMID 34361142, 2021). "MYCN has been extensively studied in neuroblastoma where it marks a subset of high-risk children with poor prognosis despite intensive multi-modal therapy." (PMID 34262099, 2021). "IMR32, MYCN amplified neuroblastoma cells, showed broad susceptibility to epigenetic targeting compounds." (PMID 33968920, 2021). "As expected for a representative neuroblastoma cohort, stage/risk group, age and MYCN status were each prognostic of outcome in both cohorts (p < 0.001)." (PMID 33918978, 2021). "High risk neuroblastoma exhibits genetic features that include deletion of chromosome arm 1p, gain of parts of 17q, aneuploidy and amplification of the proto-oncogene MYCN, and deletion of parts of chromosome arm 11q." (PMID 34885007, 2021). "Experimental results in transgenic mouse models have identified activating ALK mutations and MYCN overexpression as the main oncogenic drivers of neuroblastoma." (PMID 34638328, 2021). "Amplification of the MYCN oncogene is a molecular hallmark of aggressive neuroblastoma (NB), a childhood cancer of the sympathetic nervous system." (PMID 34016720, 2021). "SOX11, the locus which maps to the short arm of chromosome 2, which is often gained together with MYCN amplification in high-risk neuroblastoma, is a key oncogenic factor in multiple cancer entities including mantle cell lymphoma." (PMID 34638267, 2021). "Amplification of the proto-oncogene MYCN is a key molecular aberration in high-risk neuroblastoma and predictive of poor outcome in this childhood malignancy." (PMID 34847775, 2021). "Complete surgical removal of the primary tumor proved to be beneficial for high-risk neuroblastoma patients assigned to the high-risk category solely by MYCN amplification." (PMID 34503173, 2021). "High expression of MYCN protein associates with highly aggressive neuroblastoma in a group of patients, and overexpression of MYCN in developing neuroblasts spontaneously triggers the growth of aggressive undifferentiated neuroblastoma tumors." (PMID 34957126, 2021). "Our results showed that JVG045 is rather specific in targeting K-Ras mutated pancreatic cancer cells and MYCN amplified neuroblastoma cells." (PMID 33287862, 2020). "In practice, several clinical parameters, such as age at diagnosis, tumor stage, genomic amplification of MYCN oncogene, and ploidy, are widely used as the markers of neuroblastoma risk." (PMID 32731407, 2020). "Conversely, each 1.7 cm increase in genetically predicted adult height attainment was associated with a 0.86‐fold decrease in MYCN‐amplified neuroblastoma risk." (PMID 32945147, 2020). "Acquired genomic alterations, including MYCN amplification and 1p alteration, are important risk factors for neuroblastoma." (PMID 32696122, 2020). "Focal amplification of MYCN occurs in roughly 40–50% of high-risk neuroblastoma cases and is associated with an aggressive phenotype and poor prognosis." (PMID 32211329, 2020). "Loss of miR-34a at chromosome band 1p36, a region frequently deleted due to loss of heterozygosity in neuroblastoma cells, is associated with MYCN amplification and promotion of tumor aggressiveness." (PMID 33937011, 2020). "Although the overall mutational burden in neuroblastoma is very low compared to other cancer types, high-risk disease is often characterized by amplification of the oncogenic driver MYCN." (PMID 33117806, 2020).